PANX1 (pannexin 1)
Diseases named in the same sentence as PANX1 in open-access papers (continued):
Sharing a sentence is not in itself a finding about the gene and the disease.
cardiac failure (2 papers, 2024 to 2026). "Panx1, specifically in endothelial cells, contributes to the chronic I/R response that leads to heart failure." (PMID 41569301, 2026). "Spironolactone, a mineralocorticoid receptor antagonist used for the treatment of heart failure, hypertension, edema, and primary hyperaldosteronism, is another pharmacological agent known to inhibit Panx1." (PMID 41569301, 2026). "Respiratory and cardiac failure are the main causes of death in DMD patients and Panx1 is expressed in the heart and lungs." (PMID 38671506, 2024). "However, potential synergistic actions of Panx1 inhibition and mineralocorticoid receptor antagonism on spironolactone’s mechanisms of action in heart failure have yet to be concretely defined." (PMID 41569301, 2026).
cardiac hypertrophy (2 papers, 2019 to 2024). "Compared with WT and Panx1−/− mice, Cx40−/−Panx1−/− mice exhibit cardiac hypertrophy, and significantly elevated arterial blood pressure that phenocopies Cx40−/− mice." (PMID 30745457, 2019). "Cx40−/− and Cx40−/−Panx1−/− mice exhibited elevated cardiac hypertrophy and were severely hypertensive compared with Panx1−/− and WT mice, despite no observable decrements in in vivo cardiac function as assessed by echocardiography." (PMID 30745457, 2019). "Despite the lack of fibrosis, cardiac hypertrophy may also be accompanied by connexin expression remodeling, thus WT, Cx40−/−, Panx1−/−, and Cx40−/−Panx1−/− hearts were examined for molecular anomalies at the intercalated discs (ICDs) which may manifest as changes in Cx43 location." (PMID 30745457, 2019).
cardiac ischemia (2 papers, 2020 to 2025). "Myocardial ischemia and reperfusion can lead to GJCs closure and this is contrasted with HCs and Panx1 channel opening." (PMID 33383853, 2020). "Cellular stress, including myocardial ischemia, enhances cardiomyocyte ATP release through the Panx1 channels that facilitate early fibroblast activation." (PMID 33383853, 2020).
deafness (2 papers, 2017 to 2018). An inherited or acquired condition characterized by the complete loss of the ability to hear from one or both ears. "The P2X2 dominant deafness mutations may have a negative effect on Panx1 leading to hearing loss." (PMID 29180951, 2017).
diabetic kidney disease (2 papers, 2022 to 2026). Progressive kidney disorder caused by vascular damage to the glomerular capillaries, in patients with diabetes mellitus. "We studied the expression of connexin 43 (Cx43) and pannexin 1 (PANX1) in different cellular populations of the kidneys of diabetic mice and diabetic and non-diabetic patients, to evaluate their role as potential therapeutic targets in diabetic kidney disease (DKD)." (PMID 41828379, 2026).
endothelial dysfunction (2 papers, 2019 to 2020). In vascular diseases, endothelial dysfunction is a systemic pathological state of the endothelium (the inner lining of blood vessels) and can be broadly defined as an imbalance between vasodilating and vasoconstricting substances produced by (or acting on) the endothelium. "Our data show that the Panx1-400C SNP predisposes for the development of endothelial dysfunction and reduced myocardial perfusion during stress (induced by CPT or dipyridamole-induced hyperemia) with increasing BMI in non-obese subjects." (PMID 32023876, 2020). "Although multiple studies in mice point to a role for Panx1 in vascular pathologies caused by impaired endothelial function, whether the Panx1-400A>C SNP associates with endothelial dysfunction in humans is presently unknown." (PMID 32023876, 2020). "The present study shows for the first time an implication of the Panx1-A400C SNP in endothelial dysfunction and reduced myocardial perfusion under stress." (PMID 32023876, 2020). "Here, we aimed to evaluate the potential implication of this Panx1 genetic variant in endothelial dysfunction and myocardial perfusion in obese and non-obese individuals." (PMID 32023876, 2020). "Here, we demonstrated that Panx1-400C SNP predisposes to BMI-dependent endothelial dysfunction in non-obese subjects." (PMID 32023876, 2020). "The long lasting (>1 h) activation of Panx-1 channels and further O2• −-mediated recruitment of connexin hemichannels may lead to endothelial dysfunction." (PMID 31138827, 2019). "We investigated whether the Panx1-400A>C single nucleotide polymorphism (SNP), encoding for a gain-of-function channel, associates with endothelial dysfunction in non-obese and obese individuals." (PMID 32023876, 2020). "Therefore, we hypothesized that the prolonged increase in the activation of Panx-1 channels and connexin hemichannels may trigger endothelial dysfunction and the inhibition of NO signalling evoked by capsaicin." (PMID 31138827, 2019). "Altogether, our results demonstrate that for non-obese Panx1-400C subjects, elevation in triglyceride and insulin concentrations as well as increased HOMA promote endothelial dysfunction and a reduction in MFR, effects that are absent or even slightly inverted in non-obese Panx1-400A subjects." (PMID 32023876, 2020).
gallbladder carcinoma (2 papers, 2016 to 2023). "Additionally, using Ki67 labeling along with Panx1 immunostaining, the authors concluded that Panx1 expression was negatively correlated with proliferation in gallbladder carcinomas." (PMID 27229305, 2016).
leukemia (2 papers, 2021 to 2025). A malignant (clonal) hematologic disorder, involving hematopoietic stem cells and characterized by the presence of primitive or atypical myeloid or lymphoid cells in the bone marrow and the blood. "However, PANX1 gene expression findings in leukemia are inconsistent." (PMID 34796785, 2021).
liver cancer (2 papers, 2021 to 2025). An epithelial or non-epithelial malignant neoplasm that arises from the liver. "PANX1 overexpression has been associated with a worse prognosis in breast and liver cancer patients, which mechanistically is linked to PANX1-dependent enhancement of epithelial–mesenchymal transition and thus cell invasion." (PMID 34439480, 2021).
lung fibrosis (2 papers, 2013 to 2024). "Recent animal studies have identified the importance of P2X7 receptor and pannexin-1 complex in IL-1β maturation, inflammation and evolution to pulmonary fibrosis." (PMID 23634990, 2013).
multiple myeloma (2 papers, 2019 to 2020). "For example, human leukemic lymphocytes show higher levels of PANX1 in comparison to normal T cells, and high expression of PANX1 has been reported across aggressive multiple myeloma cell lines." (PMID 30654593, 2019). "Thus, inflammasome/pyroptosomes activation and cleavage of GSDMD and PANX1 are likely to induce pore formation leading to the “ballooning” morphology and the subsequent release of LDH and IL-1b seen in the drug treated myeloma cells." (PMID 33066043, 2020).
Parkinson disease (2 papers, 2022 to 2023). A progressive degenerative disorder of the central nervous system characterized by loss of dopamine producing neurons in the substantia nigra and the presence of Lewy bodies in the substantia nigra and locus coeruleus. "These similarities provide potential avenues of insight into the connection between PANX1 and various neurological conditions such as the link between vesicle-mediated transport genes and Parkinson’s disease risk." (PMID 37807670, 2023). "These potential links between PANX1, vesicle transport, and Parkinson’s disease may be worth pursuing given the cell-to-cell propagation of alpha-synuclein fibrils, implicated in Parkinson’s disease, involves macropinocytosis, a process in which PANX1 has been implicated." (PMID 37807670, 2023). "The connection to Parkinson’s disease is further bolstered by our PANTHER pathway analysis, which identified Parkinson’s disease as one of six pathways exhibiting enrichment within the PANX1 interactome." (PMID 37807670, 2023).
primary ovarian failure (2 papers, 2021). Absent or premature cessation of ovarian function due to a pathologic process originating within the ovaries. "The first human patient identified to harbor a homozygous genetic variant in PANX1 (PANX1-R217H) suffers from a staggering number of maladies in several of the organs most highly enriched in PANX1, including severe neurological deficits and primary ovarian failure." (PMID 33937260, 2021).
Renal cyst (2 papers, 2023 to 2025). A fluid filled sac in the kidney. "The beneficial effects of probenecid on attenuation of renal cysts' progression in Pkd1RC/RC mice demonstrated the potential significance of PANX1 hemichannel as a drug target." (PMID 37024297, 2023).
thrombosis (2 papers, 2020 to 2022). "Venous thromboembolism after injection of collagen/epinephrine in the jugular vein and reduced FeCl3-induced thrombosis in mesenteric arteries were observed in platelet-specific PANX1 knockout mice suggesting a functional role of platelet Panx1 channels in hemostasis and thrombosis in vivo." (PMID 35563450, 2022). "More recently, the impact of platelet PANX1 in thrombosis and hemostasis has been confirmed using platelet-specific PANX1 knockout mice (Panx1(fl/fl)/PF4-cre+) that display extended bleeding times and defective arterial thrombosis in vivo." (PMID 33114406, 2020).
tongue cancer (2 papers, 2021 to 2023). A malignant neoplasm affecting the tongue. "The purpose of this study was to investigate the contribution of PANX1 to nociception in tongue cancer." (PMID 34768835, 2021). "It is highly possible that PANX1 is a therapeutic target for the development of appropriate drugs to prevent tongue cancer pain." (PMID 34768835, 2021). "In this context, a PANX1 inhibitor could potentially be useful as a new treatment for tongue cancer pain." (PMID 34768835, 2021). "Thus, we hypothesized that PANX1 in Vc microglia is involved in the development of tongue cancer pain." (PMID 34768835, 2021). "We could not rule out the possibility that the microglial PANX1 is involved in tongue cancer pain." (PMID 34768835, 2021).
abscess (1 paper, 2013). An inflammatory process characterized by the accumulation of pus within a newly formed tissue cavity which is the result of a bacterial, fungal, or parasitic infection or the presence of a foreign body. "Reactive astrocytes immediately bordering an abscess exhibited open Panx1 channels during the acute inflammatory period, which dissipated as the infection evolved." (PMID 23390418, 2013).
amyloidosis (1 paper, 2021). A disorder characterized by the localized or diffuse accumulation of amyloid protein in various anatomic sites. "Strikingly, although LTP was impaired in Aβ-treated wt hippocampi, LTP was unaffected by Aβ-treatment in Panx1-ko, suggesting that the absence of Panx1 may be beneficial in the early stages of amyloidosis that accompany AD progression." (PMID 33796018, 2021).
aneurysm (1 paper, 2022). Bulging or ballooning in an area of an artery secondary to arterial wall weakening. "Therefore, the reduction of arterial pressure is a Panx1-dependent action that is plausibly associated with the decrease in aneurysm formation and subsequent risk of death from aneurysm rupture." (PMID 35315432, 2022). "The current study defines a mechanistic aspect of AAA formation mediated by Panx1 channels on endothelial cells as a pivotal regulator of aortic inflammation and vascular remodeling observed during the pathogenesis of aneurysm formation." (PMID 35315432, 2022). "Furthermore, pharmacological treatment with a Panx1 inhibitor (probenecid) substantially mitigates aortic inflammation and remodeling to attenuate aneurysm formation in two separate established models of murine AAA." (PMID 35315432, 2022).
aortic aneurysm (1 paper, 2022). A ruptured aneurysm located in the wall of the proximal portion of the descending aorta proceeding from the arch of the aorta. "Pannexin-1 ion channels on endothelial cells regulate vascular inflammation and remodeling to mediate aortic aneurysm formation." (PMID 35315432, 2022). "Panx1 expression is upregulated in human AAAs and retrospective clinical data demonstrated reduced mortality in aortic aneurysm patients treated with Panx1 inhibitors." (PMID 35315432, 2022). "Collectively, these data identify a mechanistic role of Panx1 channels in aortic aneurysm formation." (PMID 35315432, 2022). "The mechanistic signaling involving the concurrent activation of Panx1, P2X/Y, and TRPV4 channels could account for the slow and sustained development of chronic aortic pathologies, i.e., aortic aneurysms." (PMID 35315432, 2022).
Arterial thrombosis (1 paper, 2022). The formation of a blood clot inside an artery. "Since PANX1 is also expressed at the surface of other blood cells such as RBCs and leukocytes, which also contribute to thrombus formation, the platelet-specific deletion of PANX1 might be the best model to analyze the role of PANX1 in arterial thrombosis." (PMID 35563450, 2022). "Thus, PANX1 channels may serve as a novel therapeutic target against arterial thrombosis." (PMID 35563450, 2022).
astrocytoma (1 paper, 2011). "In this same study, the high K+-induced influx of YoPro1 in 1321N1 astrocytoma was also shown to be totally prevented in cells in which Panx1 was knocked-down by shRNA." (PMID 21949881, 2011).
autism (1 paper, 2012). Persistent deficits in social interaction and communication and interaction as well as a markedly restricted repertoire of activity and interest as well as repetitive patterns of behavior. "Additionally, our results point specifically to SLC25A12 and PANX1/2 and to pathways (such as, methyltransferase, ribosomal components) previously implicated in autism." (PMID 22591576, 2012). "Additionally, the data implicates individual genes SLC25A12, PANX1 and PANX2 as well as pathways previously implicated in autism." (PMID 22591576, 2012).
Blindness (1 paper, 2014). Blindness is the condition of lacking visual perception defined as a profound reduction in visual perception. "This research is currently driven by the availability of knock out animal models, sophisticated ex vivo and in vitro preparations suitable to address the emerging roles of Panx1 in a physiological or pathological context, and the potential implication of Panx1 in leading causes of blindness." (PMID 25309318, 2014).
breast tumors (1 paper, 2016). "Thus, PANX1 mRNA levels in breast tumors was correlated with clinical outcomes." (PMID 27099931, 2016).
cerebral edema (1 paper, 2017). "Probenecid, as an inhibitor of Panx1 channels, inhibits ATP release induced by Panx1 activation, blocks inflammasome formation, and attenuates caspase 1 cleavage, thereby alleviating neuronal death and reducing brain inflammation and cerebral edema." (PMID 29054968, 2017).
cerebrovascular diseases (1 paper, 2017). "In addition, given the current research is a pilot study, further studies are still needed to validate the exact role of Pannexin-1 channels in SAH and other cerebrovascular diseases." (PMID 28634441, 2017).
Chlamydia infections (1 paper, 2013). "As the inflammasome has been implicated in the progression of Chlamydia infections, and with chlamydial infections at record levels in the US, we therefore investigated whether probenecid would have a direct effect on Chlamydia trachomatis development through inhibition of Panx1." (PMID 23700432, 2013).
cholangiocarcinoma (1 paper, 2021). A carcinoma that arises from the intrahepatic biliary tree (intrahepatic cholangiocarcinoma) or from the junction, or adjacent to the junction, of the right and left hepatic ducts (hilar cholangiocarcinoma). "In the present study, PANX1 was shown to have a negative correlation with CD160 in various tumors, such as LGG (rho = −0.480, P < 2.2e-16), KIRP (rho = −0.371, P = 9e-11) and cholangiocarcinoma (CHOL) (rho = −0.41, P = 0.0137)." (PMID 34796785, 2021).
cognitive disease (1 paper, 2022). "Here, we discuss the mechanisms associated with Pannexin-1 channel opening within the circulation, as well as within the resident viral reservoirs, ATP dysregulation, and cognitive disease observed in the HIV-infected population." (PMID 35883688, 2022).
colorectal adenocarcinoma (1 paper, 2020). The most common type of colorectal carcinoma. "Moreover, knockout of PANX1 also suppressed the decrease in ATP during TRAIL-induced apoptosis of SW480 human colorectal adenocarcinoma cells." (PMID 33052098, 2020).
cutaneous squamous cell carcinoma (1 paper, 2025). "Abstract figure legend PANX1 and PANX3 show opposite expression patterns in patient‐derived normal skin and cutaneous squamous cell carcinoma (cSCC) tumours, with PANX1 increased and PANX3 mRNA decreased in cSCC tumours compared to skin." (PMID 39560179, 2025). "PANX1 and PANX3 function in skin homeostasis and keratinocyte differentiation but were previously reduced in a small cohort of human cutaneous squamous cell carcinoma (cSCC) tumours compared to normal epidermis." (PMID 39560179, 2025).
cystitis (1 paper, 2023). Inflammation of the urinary bladder. "Like PANX1, P2X7R plays a role in activating and sustaining inflammation and has been implicated in several inflammatory and autoimmune diseases and cancer, including in the inflammatory processes of animal models of cyclophosphamide or acrolein-induced cystitis." (PMID 37373111, 2023). "Thus, while stretch-activated PANX1 hinders s-ENTDS release possibly to preserve effective ATP concentration at the end of bladder filling, P2X7R activation, presumably in cystitis, would facilitate s-ENTDs-mediated ATP degradation to counteract excessive bladder excitability." (PMID 37373111, 2023).
familial cold autoinflammatory syndrome (1 paper, 2022). Familial cold urticaria (FCAS) is the mildest form of cryopyrin-associated periodic syndrome (CAPS) and is characterized by recurrent episodes of urticaria-like skin rash triggered by exposure to cold associated with low-grade fever, general malaise, eye redness and arthralgia/myalgia. "Pannexin 1 inhibition prevents familial cold autoinflammatory syndrome-associated NLRP3 mutant-mediated inflammasome assembly." (PMID 35616535, 2022).
glioblastoma (1 paper, 2025). The most malignant astrocytic tumor (WHO grade IV). "Probenecidsol, an uricosuric agent, suppresses glioblastoma proliferation by inhibiting pannexin-1 channels in tumor cells." (PMID 40535121, 2025).
Glucose intolerance (1 paper, 2024). Glucose intolerance (GI) can be defined as dysglycemia that comprises both prediabetes and diabetes. "Ad-PANX1 injection inhibited hepatic glucose production, improved glucose intolerance, decreased fasting hyperglycemia (P < 0.05), and enhanced global insulin sensitivity in mice." (PMID 38937853, 2024). "The injection of Ad-PANX1 markedly reduced hepatic glucose production and improved glucose intolerance in db/db mice (P < 0.01)." (PMID 38937853, 2024).
HIV-1 infection (1 paper, 2022). The type species of lentivirus and the etiologic agent of acquired immunodeficiency syndrome (AIDS). "Accordingly, blocking just one of the pathway constituents (e.g. Panx-1, ATP, P2Y2 or Pyk2) caused a decrease in HIV-1 infection and replication efficiency." (PMID 35784277, 2022).
Hyperglycemia (1 paper, 2024). An increased concentration of glucose in the blood. "Notably, long-term hepatic FAM3A overexpression failed to improve the impaired glucose tolerance and elevated fasting hyperglycemia in PANX1-deficient mice." (PMID 38937853, 2024).
hypertensive nephropathy (1 paper, 2024). Kidney damage that results from chronically elevated blood pressure; complications include glomerular damage resulting in proteinuria and hematuria. "This study aimed to investigate the impact of Panx1 channels on mesangial cell function in the context of hypertensive nephropathy." (PMID 38660621, 2024).